RIMOC1 (RAB7A interacting MON1-CCZ1 complex subunit 1)
Description:
Plays an important role in the removal of damaged mitochondria via mitophagy by controlling the stability and localization of RAB7A. Required for the recruitment of RAB7A and ATG9A vesicles to damaged mitochondria and promotes the stability of RAB7A by inhibiting its proteasomal degradation during mitophagy.
Synonyms: C5orf51; LOC285636
Tractability: PROTAC: ubiquitination databases record sites on it.
Gene: Protein-coding gene on chromosome 5 (41,904,188 to 41,921,636, forward strand). Ensembl gene ENSG00000205765.
Subcellular location: Cytoplasm, cytosol
Subcellular location (Human Protein Atlas): Nucleoplasm; Cytosol
Gene Ontology:
Molecular function: protein binding
Biological process: mitophagy
Cellular component: cytosol; nucleoplasm
Genetic constraint (gnomAD): Loss-of-function variants: 12 observed, 23.52 expected, observed/expected ratio (o/e) 0.51, 90% interval 0.33 to 0.83. The upper end of that interval is the gene's LOEUF score, 0.83, which puts it in group 3 of 6, group 1 being the genes least tolerant of losing a copy. Missense variants: 219 observed, 248.52 expected, observed/expected ratio (o/e) 0.88, 90% interval 0.79 to 0.99. Synonymous variants: 91 observed, 87.93 expected, observed/expected ratio (o/e) 1.03, 90% interval 0.87 to 1.23.
Homologues: Orthologues: chimpanzee RIMOC1 (99% identical), guinea pig RIMOC1 (94% identical), dog RIMOC1 (92% identical), mouse Rimoc1 (89% identical), rat Rimoc1 (89% identical), rabbit RIMOC1 (84% identical), pig RIMOC1 (79% identical), zebrafish rimoc1 (44% identical).
Diseases named in the same sentence as RIMOC1 in open-access papers:
RIMOC1 is named in the same sentence as 2 diseases in open-access papers, as found by Europe PMC text mining. Sharing a sentence is not in itself a finding about the gene and the disease.
RIMOC1 shares sentences with these, for which no sentence is quoted: Alzheimer disease (1 paper); thalassemia (1).